NES (nestin)
Diseases named in the same sentence as NES in open-access papers (continued):
Sharing a sentence is not in itself a finding about the gene and the disease.
glioma (continued). "Previous studies have similarly observed nestin staining of the vasculature in primary low grade glioma samples." (PMID 24349039, 2013). "Under serum spheroid conditions, the majority of cells from all xenografts was positive for human nestin as would be expected from a human glioma cell population." (PMID 24349039, 2013). "Nestin is a type VI intermediate filament protein and its expression is restricted to central nervous system precursor cells, such as neural and glioma stem cells." (PMID 23251243, 2013). "Blood microvessels in the tumor xenograft core stained intensely for mouse nestin, which suggests the contribution of host mouse nestin-positive cells to glioma angiogenesis." (PMID 22539956, 2012). "Nestin has been shown to be a strong prognostic marker for glioma malignancy and its expression correlates with patient survival." (PMID 22995409, 2012). "In low-generation invasive glioma lesions, nestin-expressing single cells with astrocytic or bipolar morphology were richly interwoven between infiltrating tumor cells." (PMID 22539956, 2012). "Both CD133+ blood vessels and nestin+ blood vessels have an important role in maintaining glioma stem cell niche structure." (PMID 22973309, 2012). "The observation that rodent nestin-positive cells were recruited to the parenchyma and neovasculature of glioma xenografts suggests a ‘crosstalk’ between the human tumor and rodent host compartments." (PMID 22539956, 2012). "Our data demonstrate a robust migration of nestin-expressing host cells to glioma, which together with pericytes give rise to tumor vasculature." (PMID 22539956, 2012). "In the U87 human glioma xenograft model, both the primary lesion and small tumor satellites stained uniformly for human nestin." (PMID 22539956, 2012). "They noted that CD133+ and nestin+ niches are localized perivascularly in all glioma tissues and that blood vessels were also nestin− and CD133+." (PMID 22973309, 2012). "Similar to what we observed in glioma cell-line implants in mice, glioma xenografts in rats displayed a halo of nestin-positive host cells that was localized to the tumor border and peritumor areas." (PMID 22539956, 2012). "In both mice and rats, a host nestin-positive cell population (endothelial progenitors) contributes to human xenograft growth by assembling into the glioma microvasculature." (PMID 22539956, 2012). "The mechanism of activity of the combination of cediranib and AZD1480 however is not exclusively confined to the inhibition of STAT3 expressing macrophages in the glioma since the combinational approach also inhibited nestin." (PMID 23013619, 2012). "In both models, the xenografts recruited large numbers of host nestin-expressing cells, which formed a ‘network’ with glioma." (PMID 22539956, 2012). "Nestin has been detected in human gliomas, with expression more frequent in high-grade gliomas than in low-grade gliomas such as pilocytic astrocytomas." (PMID 22580387, 2012). "In this study, we found that a human tumorigenic glioma cell line LN-229 grew as a monolayer culture and expressed nestin at a very low level under serum-free conditions." (PMID 22330721, 2012). "Mouse nestin-positive cells were incorporated into vessels both in the periphery and core of U87 human glioma xenografts." (PMID 22539956, 2012). "We observed that host stem/progenitor cells identified by rodent nestin expression displayed tropism for human glioma xenografts in both mice and rats, and that host cells originated and migrated from the ipsilateral SVZ to xenografts." (PMID 22539956, 2012). "The areas that were devoid of human or mouse nestin-expressing cells, likely contained other cell types of the tumor stroma or extracellular matrix, which comprise a large portion of the tumor bed in gliomas." (PMID 22539956, 2012).
glioma (continued). "When the STAT3 pathway is blocked in the setting of VEGF inhibition in mice with intracerebral gliomas, glioma volume is reduced and the additive effect correlated with inhibition of nestin and glioma-infiltrating macrophages." (PMID 23013619, 2012). "Double-staining for human nestin (tumor) and mouse nestin (infiltrating host cells) revealed an interdigitation of host nestin-positive cells with human glioma cells in the tumor." (PMID 22539956, 2012). "CD133+/Nestin+ cells in both gliomas and MB can survive radiation therapy by activating their Akt pathway." (PMID 21931765, 2011). "RCAS/tv-a is a retroviral system that allows for lineage tracing from the nestin-positive glioma cell-of-origin, and the use of this specific vector labels the cell-of-origin and its progeny with eGFP expression." (PMID 21754979, 2011). "All experiments for this study utilized the RCAS/tv-a system to generate PDGF-B driven gliomas in nestin-t-va/ink4a-arf-/-/ptenfl/fl mice." (PMID 21267448, 2011). "Stereotactic injection of RCAS vector-mediated PDGF-induced gliomas from nestin-expressing cells shows similar incidence and latency when injected in the SVZ and the cortex of adult mice." (PMID 21931722, 2011). "Our data (not included) as well as others, have shown in low-grade glioma, despite a higher proportion of tumors demonstrating low nestin expression, a significant number of these specimens do express nestin highly." (PMID 18817556, 2008). "In our work, in agreement with literature data, Nestin was expressed more frequently in higher malignant grade gliomas by tumor cells, being predictive of a significantly lower 5-year survival rate." (PMID 19108713, 2008). "The association of Nestin and CD133 expression with the 5-year survival rate of patients with gliomas was analyzed using Kaplan-Meier analysis." (PMID 19108713, 2008). "Other investigators have suggested a more definitive correlation of nestin expression with decreased overall survival, although these studies included all high-grade glioma." (PMID 18817556, 2008). "Although initially identified in glioma, nestin expression has since been demonstrated in several other malignancies, including angiosarcoma, gastrointestinal stromal tumors (GIST), hemangioblastomas, melanoma, and basal epithelial breast cancer." (PMID 18817556, 2008). "Immunocytochemical analysis of BTICs established from five glioma patients expressed the early neural cell progenitor proteins Nestin, Musashi, hSox2, and CD133 (J. J. P. Kelly, S. Weiss, P. A. Forsyth, and D. L. Senger; unpublished data)." (PMID 19067488, 2008). "With the significantly more heterogeneous clinical outcomes in low-grade glioma, defining the prognostic value of nestin in this population would be of particular interest." (PMID 18817556, 2008). "The typical pattern of nestin filament organization, i.e. the asymmetric position of the nestin-positive region in the cytoplasm near the nucleus, which we observed, has also been detected in U-373 and U-251 human glioma cell lines." (PMID 16457706, 2006). "Notably, the expression of β-catenin and Wnt-1 was significantly reduced in the combination group, followed by a significant downregulation of Nestin and β3-tubulin, markers of glioma stem-like cells and aggressiveness, respectively." (PMID 41693444, 2026). "The Notch signal pathway can activate the nestin promoter, leading to upregulate nestin and promoting the proliferation of nestin+ embryonal brain tumors cells, and even promoting the stemness, proliferation, and impaired differentiation of glioma stem cells." (PMID 40799240, 2025). "Furthermore, several studies have found that Nestin expression is related to the degree of glioma malignancy." (PMID 40809181, 2025). "In gliomas, high nestin expression correlates with higher tumor malignancy and worse prognosis." (PMID 40559213, 2025).
glioma (continued). "In addition, the analytic data from the CGGA database (in mRNASeq‐325) also showed that Sohlh1 expression in glioma tissues was negatively correlated with the expression of Nestin, a stemness marker." (PMID 40418209, 2025). "Immunocytochemistry for neuronal (neurofilament) and glioma (nestin) markers, together with a presynaptic marker (synapsin 1) and GABRG2–GFP revealed colocalization of neuronal presynaptic puncta with glioma postsynaptic GABRG2–GFP puncta by confocal microscopy." (PMID 39972132, 2025). "Interestingly, the PI3K-pathway appears to be involved in both the formation of FCDs and neuroglial tumors, and enhanced nestin mRNA was observed in FCDs with balloon cells and GG." (PMID 38846038, 2024). "In single samples, TrkB appeared in Nestin+ cells, at least in certain areas of glioma tissue." (PMID 39039193, 2024). "A previous study on glioblastoma showed that knockdown of MerTK disrupted the rounded morphology of glioma cells with a decrease in tumor stem cell markers, such as Sox2 and Nestin, indicating that MerTK could maintain cells in an undifferentiated state." (PMID 38545840, 2024). "Consequently, we found an increase in the expression of GFAP, but a decrease in the expression of Nestin and two markers of glioma stem cells, CD133 and CD44, indicating that low expression of OGDH promotes glioma cell differentiation." (PMID 39872214, 2024). "Although both low‐grade and high‐grade tumors were shown to express Nestin in a different study, the majority of gliomas with high levels of Nestin expression were high‐grade gliomas, including glioblastomas, anaplastic oligodendrogliomas, anaplastic astrocytomas, and anaplastic oligoastrocytomas." (PMID 38925618, 2024). "Moreover, a retrospective study that analyzed nestin-expressing cells in 102 patients with glioma observed that proliferating endothelial cells expressing nestin correlate to histological grade and clinical outcome." (PMID 37887005, 2023). "Reports of significant correlation of its expression with tumor behavior and patient prognosis have yielded mixed results, although a large meta-analysis found that nestin expression significantly correlated with poorer prognosis in patients with gliomas of various tumor grades (II-IV)." (PMID 38275375, 2023). "As an example, genetic glioma models such as PDG-Ink4a, which is induced by RCAS-vectors encoding PDGFB in Nestin-Tv-a; Ink4a/Arf-/- transgenic mice, better recapitulate the mutational landscape of glioma patients compared to the chemically-induced GL261 glioma." (PMID 37954592, 2023). "al. emphasized the involvement of SNAI2 in glioma cell stem-like properties; A decrease in SNAI2 elicited by overexpressed miR-124 contributed to a reduction in the CD133(+) cell subpopulation and decreased Nestin expression, while suppressing the in vivo tumorigenicity and invasion of glioma cells." (PMID 35654777, 2022). "In addition, neural stem cell marker proteins CD133 and Nestin have also been found to be marker proteins of glioma stem cells, and their high expression is crucial for the self-renewal and proliferation of GSCs." (PMID 35927251, 2022). "Western blot analysis demonstrated that the CD133 and Nestin protein levels in CD133+ glioma stem cells were significantly higher than those in CD133- glioma cells, whereas the protein level of LASS2 in CD133+ glioma stem cells was significantly lower than that in CD133- glioma cells." (PMID 35517425, 2022). "By confocal imaging we could demonstrate a co-expression of CD133 and Nestin within recurrent glioma cells." (PMID 35183162, 2022). "Together, those results indicated that suppressing SOX2 and Nestin signaling by the integrin αvβ3 inhibitor efficiently improved the anticancer effects of the conventional chemotherapeutic agent, providing an innovative approach in glioma therapy." (PMID 33408794, 2021).
glioma (continued). "It is known that Notch-1 promotes nestin expression in glioma cells and inhibits their differentiation, so the involvement of Notch-1 in R2J-GS cell activity would also be of interest to better understand the workings underlying the expression of these markers." (PMID 34638987, 2021). "Next, glioma cells were isolated from three GBM patients, and patient-derived glioma cells (PD-G) were stimulated into glioma stem cells (PD-GSCs), which were identified by Nestin staining and pluripotent differentiation ability after culture in complete medium containing FBS." (PMID 34512162, 2021). "It was observed that a significantly higher proportion of migrating cells treated with Tf@pSiNPs expressed nestin compared to the control, suggesting that these cells could be of glioma CSC origin." (PMID 33637089, 2021). "Nestin is also discussed as playing a role in the cell survival and proliferation of cancer stem cells, and has been shown to be a strong prognostic factor for glioma malignancy." (PMID 34681783, 2021). "Although tumors of high-grade glioma patients expressed majorly nuclear Survivin, they exhibited rarely NES mutations which did not correlate with survival." (PMID 34100981, 2021). "Interestingly, in this matrix, glioma stem cells were able to maintain key stemness biomarkers (e.g., Nestin), and at the same time, cells exhibited some glial differentiation and increased VEGF secretion over time." (PMID 33643799, 2021). "Moreover, PDGFB-induced glioma primary cells (PIGPC) derived from RCAS-PDGFB-induced gliomas in Nestin-tv-a Ink4a/Arf-/- mice showed increased colony numbers, as well as visibly larger colonies when cultured on ADM1 compared to colonies formed on ADM21." (PMID 33802060, 2021). "Nestin is an intermediate filament expressed specifically in glioma." (PMID 34372614, 2021). "Nestin, a class VI intermediate filament protein, is a marker for glioma stem cells." (PMID 33637089, 2021). "We concluded that PpIX fluorescence is more common in nestin+ glioma cells." (PMID 33959713, 2021). "Nestin, an intermediate filament, is a molecular marker of malignant glioma (expression was confirmed in 6 out of 6 human glioma lines and in 3 out of 4 primary glioma cells)." (PMID 33535555, 2021). "This suggests that nestin+ glioma cells contribute to PpIX fluorescence." (PMID 33959713, 2021). "Immunofluorescence staining of glioma and normal brain tissue chips further confirmed that ACE2 expression co-localized with CD31, CD73, and nestin, which confirmed the susceptibility to SARS-CoV-2 of nervous system cells, including ECs, BMSCs, and NPCs, from clinical specimens." (PMID 33312949, 2020). "Thus, nestin promoter is expected to drive expression of functional ICP34.5 selectively in glioma cells, resulting in a cytopathic effect." (PMID 33322507, 2020). "Nestin on the other hand has been assessed more extensively in gliomas." (PMID 32160197, 2020). "Furthermore, nestin expression has also been reported in a wide array of tumors including breast cancer, lung cancer, glioma, melanoma, and pancreatic cancer." (PMID 31675305, 2019). "This might be of further interest, as nestin was especially found in cells at the invasive front of glioma." (PMID 31003495, 2019). "Furthermore, Notch1, Hes1 and CXCR4 expressing cells colocalized with or adjacent to the Nestin expressing glioma cells." (PMID 31382985, 2019). "While the amount of vimentin and the glioma stem cell marker nestin showed a negative correlation with patient prognosis and/or glioma staging, an association of GFAP expression with staging is controversial." (PMID 31003495, 2019). "The membrane form of Nestin was also observed on human glioma stem cells." (PMID 30279357, 2018).
glioma (continued). "We report that the GBM cells maintained in stem-cell medium displayed phenotypes consistent with immature glioma stem-like cells, characterized by growth as neurospheres, increased proliferation and elevated expression of nestin, but diminished lineage differentiation markers." (PMID 29967607, 2018). "Nestin+ cells appear in all stages of ENU-glioma but CD133 only from stage II on." (PMID 30140373, 2018). "Moreover, EGFR, phosphorylated STAT3, CD133 and Nestin expression was reduced in xenografted glioma tissues in response to honokiol treatment, which was consistent with in vitro results we observed." (PMID 30587839, 2018). "Glioma xenograft tumors were stained for the glioma stem cell marker Nestin." (PMID 29228586, 2017). "In addition, the survival rate of glioma cells and the expression of cancer stem cell markers Nestin, SSES-1, and NANOG were attenuated by WP1066." (PMID 29284440, 2017). "Here, we should note that the enhanced CD133, CD15 and NESTIN may originate from CD133+/CD15+/NESTIN+ GSCs as a result of contamination when sorting CD133−/CD15−/NESTIN− glioma cells." (PMID 28801626, 2017). "Moreover, DHA exerted a differentiating effect on T269 cells leading to a down-regulation of the stem cell markers Sox2 and nestin which argues again for its use in the combination with TMZ to better target glioma stem cells." (PMID 27447560, 2016). "We also examined CD133 and nestin that are thought to be marker proteins for glioma cell stemness." (PMID 26861698, 2016). "Although triple treatment did not further reduce CD133+ surface population compared to dual treatments, it reduced SOX2 expression a widely used marker for repopulating cells in context of radiation resistance as well as Nestin another stem cell marker in glioma progression." (PMID 27183910, 2016). "We used Meta-analysis to systematically evaluate the literatures on the relationship between the glioma stem cells markers Nestin, CD133 and the prognosis of patients with glioma in order to accurately and objectively evaluate the application value of CDl33 and Nestin in prognosis of glioma." (PMID 25967234, 2015). "Glioma CSCs could be isolated and identified by cell surface markers, such as Nestin and CD133, which were also highly expressed in our SP cells." (PMID 25763821, 2015). "The expression of nestin has been found to be an independent prognostic factor in glioma patients." (PMID 26292663, 2015). "They loaded physiologic levels of shear stress to endothelial cells and found a dramatic decrease in Nestin expression suggesting that Nestin could be a specific marker for proliferating endothelial cells in gliomas." (PMID 26236348, 2015). "Above all, we found that high CDl33 expression may be independent risk factor for glioma patients’ prognosis, especially WHO IV gliomas and high Nestin expression may be independent risk factor for glioma patients’ prognosis with grade WHO II–III." (PMID 25967234, 2015). "Based on the current findings, assessing CDl33 and Nestin expression could provide better prognostic information for patients with glioma and be used as a novel therapeutic target." (PMID 25967234, 2015). "In this study, the results showed that CSCs marker CD133 was associated with worse OS and PFS in glioma patients and Nestin was associated with worse OS but not PFS." (PMID 25967234, 2015). "Finally, CTGF was also able to induce GFAP as well as Nestin expression in a human malignant glioma stem cell line, suggesting a possible role in the differentiation process of gliomas." (PMID 26241738, 2015). "The missing information may reduce the reliability of CDl33 and Nestin expression as a prognostic indicator of glioma." (PMID 25967234, 2015).